AQP5 (aquaporin 5)
Diseases named in the same sentence as AQP5 in open-access papers (continued):
Sharing a sentence is not in itself a finding about the gene and the disease.
breast carcinoma (43 papers, 2008 to 2025). "AQP5 has been implicated in the carcinogenesis of various cancers, including breast cancer, where it contributes to proliferation, migration, and metastasis." (PMID 40244097, 2025). "Researches have shown that elevated AQP5 expression is associated with tumor lymphatic metastasis and poor prognosis, which is observed in breast cancer, gastric cancer, liver cancer, lung cancer and cervical cancer." (PMID 40760228, 2025). "The expression level of aquaporin 5 (AQP5) in breast cancer is associated with lymph node metastasis and a poor prognosis." (PMID 39233332, 2024). "The CT/TT genotype of Aqp5 rs1964676 polymorphism has been associated with strong Aqp5 expression and used as a prognostic marker of survival in patients with early breast cancer." (PMID 36768212, 2023). "In breast cancer patients, high expression of AQP5 is associated with less-favorable survival rates." (PMID 38136293, 2023). "A similar study has demonstrated a prominent AQP5 expression in breast cancer cells, while such expression was accompanied by the loss of polarity of ductal epithelial cells during the progression of breast carcinoma." (PMID 36706090, 2023). "The prominent expression of AQP5 and the loss of polarity of ductal epithelial cells were associated with the progression of breast carcinoma." (PMID 24338153, 2014). "The over-expression of AQP5 was examined recently and showed that AQP5 is significantly associated with cervical cancer, ovarian cancer, and breast cancer progression." (PMID 25217331, 2014). "A genetic study in Germany investigated the prognostic relevance of the AQP5 -1364C>A polymorphism in primary breast cancer." (PMID 24338153, 2014). "Taken together, prominent AQP5 expression in breast cancer cells with the loss of polarity of ductal epithelial cells was seen during the progression of breast carcinoma." (PMID 22145049, 2011). "Lentivirus-mediated AQP5-shRNA transduction or sorbitol-induced hyperosmotic stress in human breast cancer cells resulted in the significant reduction of AQP5 expression, which was associated with markedly decreased cell proliferation and migration." (PMID 22145049, 2011). "Therefore, a deeper understanding of AQP5’s role in breast cancer carcinogenesis and of the underlying mechanisms and conditions influencing its effects is essential." (PMID 40244097, 2025). "Consequently, AQP5 has been suggested as a potential diagnostic and prognostic biomarker and as a therapeutic target for inhibiting breast cancer progression." (PMID 40244097, 2025). "In addition, we previously demonstrated that aquaporin-5 (AQP5) expression is associated with breast cancer cell migration, activated Rac1, and cell detachment and dissemination from migrating cell sheets." (PMID 38774409, 2024). "Aquaporin 5 (AQP5) has also been found to be associated with breast cancer progression." (PMID 38785550, 2024). "Finally, we have studied gene amplifications of AQP5 as one of the causes for strong expression of AQP5 in both lung and breast cancer tissue samples." (PMID 36706090, 2023). "By fluorescence in situ hybridization (FISH), we have identified evidence of gene amplification in 3 of 30 readable breast cancer and further conclude that, in breast cancer, at least some part of AQP5 overexpression is associated with an aberration in the genome level." (PMID 36706090, 2023). "Whether the involvement of AQP5 in breast carcinogenesis is causative or merely a consequence of breast cancer cell’s need to grow, involving metabolic reprogramming and redox signalling including ROS, particularly H2O2, still needs to be elucidated." (PMID 33947079, 2021). "For example, AQP5 expression is associated with poor prognosis in breast cancer, hepatocellular carcinoma, colorectal carcinoma, chronic myelogenous leukemia, lung cancer, ovarian cancer, cervical cancer and oral squamous cell carcinoma, but to better outcome in gallbladder and biliary tract cancer." (PMID 26208856, 2015).
breast carcinoma (continued). "BrdU cell proliferation assay demonstrated that BrdU incorporation was significantly decreased (69±2% of mock control, P<0.05) in MCF7 cells with AQP5 knockdown, indicating that AQP5 knockdown in human breast cancer cells was associated with decreased cell proliferation." (PMID 22145049, 2011). "Moreover, reduction of AQP5 expression, achieved by increased osmotic stress or an inhibitory RNA, was associated with a significant reduction in cell proliferation and migration in the breast cancer cell line MCF-7." (PMID 25767807, 2015). "Importantly, prominent AQP5 labeling was associated with invasive cancer cells combined with the gradual decrease of AQP5 labeling intensity in the ductal epithelial cells during the progression of breast carcinoma." (PMID 22145049, 2011). "The overexpression of AQP5 was confirmed in all breast cancer cell lines at both the RNA and protein levels." (PMID 40244097, 2025). "Further, we were interested in how AQP5 affects cell viability across different breast cancer cell lines." (PMID 40244097, 2025). "Our study demonstrates that AQP5 overexpression enhances sensitivity to H2O2-induced oxidative stress in breast cancer cell lines, resulting in significant reductions in cell viability at 40 μM H2O2 in SkBr-3 and MCF7 cells." (PMID 40244097, 2025). "Recently, AQP1, AQP3 and AQP5 overexpression was reported to disrupt cell polarity in breast cancer by interacting with the protein Scribble, leading to its downregulation." (PMID 39941100, 2025). "In summary, our findings suggest that AQP5 overexpression in breast cancer cells under acute oxidative stress has cell-type-specific effects, with some modulation of key signaling pathways, including NRF2, PI3K/AKT, and FOXO, in response to H2O2 treatment." (PMID 40244097, 2025). "In breast cancer, AQP5 downregulates the polarity protein Scribble and activates Ras and WNT/β-catenin signaling, contributing to EMT and cancer-cell dissemination." (PMID 40244097, 2025). "Here, we aimed to investigate the role of AQP5 in the acute response of breast cancer cell lines to oxidative stress." (PMID 40244097, 2025). "Overexpression of AQP5 was successful, and levels were extremely high, as confirmed by qPCR and western blot in all breast cancer cell lines." (PMID 40244097, 2025). "The contribution of AQP1, AQP3 and AQP5 to oxidative stress resistance has been investigated in colon and breast cancer cell lines by assessing their expression before and after treatment with H2O2." (PMID 39941100, 2025). "In this study, we aimed to further investigate the role of AQP5 in the acute response of breast cancer cell lines to oxidative stress." (PMID 40244097, 2025). "We overexpressed AQP5 in breast cancer cell lines with low basal levels—HR+ (MCF7), HER2+ (SkBr-3), and TNBC (SUM 159)—and exposed them to H2O2 for 24 h." (PMID 40244097, 2025). "AQP5 was observed to be not only connected with breast cancer cell proliferation, but also with cell migration." (PMID 38336645, 2024). "In the MCF7 breast cancer cell line, knocking down AQP5 inhibited cell migration and proliferation, showing that this isoform is critical in tumour dissemination." (PMID 38336645, 2024). "AQP1 and AQP5 overexpression plays a key role in cancer cell proliferation, migration, invasion, and chemosensitivity in several breast cancer subtypes." (PMID 39123442, 2024). "Overall, this study highlights the potential of AQP5-regulating miRNAs as therapeutic agents to inhibit breast cancer cell migration, and exosome-mediated delivery as a promising approach." (PMID 38136293, 2023). "Several aquaporins are overexpressed in breast cancer, and AQP1, AQP3 and AQP5 have been linked to spread to lymph nodes and poor prognosis." (PMID 37681917, 2023). "Immunohistochemistry of resected breast cancer tissue samples for the detection of AQP5 expression was performed at the same time with tissue samples from NSCLC as control." (PMID 36706090, 2023).
breast carcinoma (continued). "Altered AQP5 expression has been observed in multiple cancer types, including lung cancer, breast cancer, and colorectal cancer." (PMID 37658903, 2023). "In this report, based on a large cohort of samples of 591 resected breast cancer samples, we have examined expression of AQP5." (PMID 36706090, 2023). "In this analysis, patients’ groups with positive AQP5 expression carried (212 cases) a less favorable breast cancer specific survival rate (p = 0.008)." (PMID 36706090, 2023). "In particular, AQP5 is likely to play an important role in the migration of human breast cancer cells and in nonsmall cancer lung cells (NSCLC)." (PMID 37223543, 2023). "This contrasts the expression of AQP5, where the staining pattern in breast cancer samples was heterogeneous." (PMID 37681917, 2023). "In this report, we have demonstrated the expression of AQP5 in breast cancer by analyzing 591 tissue samples with 7-year follow-ups." (PMID 36706090, 2023). "Of note, we recently found that AQP1, AQP3 and AQP5 differentially affected the response of 3D-grown human breast cancer spheroids to conventional anticancer therapies." (PMID 37681917, 2023). "The study for clinical implication of AQP5 expression in breast cancer was based on analyzing a TMA containing 591 BCs." (PMID 36706090, 2023). "Both of these reports suggested that AQP5 overexpression is likely to play a role in cell growth and metastasis of human breast cancer." (PMID 36706090, 2023). "Overexpression of AQP5 in MDCK cells caused disruption of 3D grown spheroids, and of note, localization of AQP5 and the major polarity protein Scribble seemed inversely correlated in human breast cancer samples." (PMID 37681917, 2023). "By contrast, in our report, among 591 patients, which included early stage, intermediate stage and late stage, from 7 years of follow up, patients’ groups with positive AQP5 expression carried (212 cases) a less favorable breast cancer specific survival rate." (PMID 36706090, 2023). "We further conclude the at least some of groups with a strong AQP5 expression in breast cancer is likely to be driven by gene amplification as seen for HER2 gene among some group of breast cancer." (PMID 36706090, 2023). "The expression of AQP1, AQP3, and AQP5 has been found to be increased among resected breast cancer samples and carries a prognostic importance." (PMID 35847914, 2022). "In ER+/progesterone receptor (PR)+ early breast cancer, AQP5 overexpression is a potential prognostic marker of patient survival." (PMID 36212456, 2022). "AQP5 inhibition also reversed ADR resistance of breast cancer and reduced the IC50 of ADR in MCF-7/ADR cells." (PMID 36212456, 2022). "AQP1, AQP3, and AQP5 mRNA expression significantly increased in breast cancer tissue compared to normal tissue and localized to the cell membranes by immunohistochemistry." (PMID 36212456, 2022). "Aquaporin 3 and aquaporin 5 are upregulated in breast cancer and certainly support processes leading to breast cancer growth and metastasis." (PMID 33947079, 2021). "Among the 13 human aquaporins, AQP3 and AQP5 were shown to be significantly upregulated in breast cancer indicating their role in the development of this malignancy." (PMID 33947079, 2021). "In the light of accumulating evidence on the role of aquaporin 3 and aquaporin 5 in breast cancer, we will bring an overview of current knowledge of these two aquaporins and their role in the regulation of redox signalling in breast cancer." (PMID 33947079, 2021). "Following a similar pattern, AQP5 upregulation by estrogen in breast cancer patients from early stages correlated with reduced survival times, suggesting AQP5 also was a prognostic marker." (PMID 32679804, 2020). "Knockdown of AQP5 activated the MAPK signaling pathway, reducing cell invasiveness and proliferation, and enhanced the chemosensitivity of breast cancer cells, suggesting AQP5 is of interest as a biomarker and a pharmacological target." (PMID 32679804, 2020).
breast carcinoma (continued). "Based on these observations, it has been suggested that AQP5 plays a role in cell growth and metastasis in human breast cancer." (PMID 25767807, 2015). "It was also shown that in benign tumor and invasive carcinoma, there is a change of AQP5 expression related to the breast cancer grade." (PMID 25767807, 2015). "In breast carcinomas, high levels of aquaporin 5 (AQP5), a membrane protein involved in water transport, have been linked to increased cell proliferation and migration, thus facilitating tumor progression." (PMID 25767807, 2015). "AQP5 over-expression was proposed as an independent prognostic marker of survival for breast cancer patients with estrogen-positive tumor." (PMID 25886458, 2015). "How AQP5 expression is controlled during different proliferative stages of the cell remains to be seen but is an important question, since it has potential implications in understanding how AQP5 is regulated in oncogenic expansions of breast cancer." (PMID 25767807, 2015). "Subsequent studies on breast cancer cell lines have shown that AQP5 is a marker protein for proliferation and migration of human breast cancer cells." (PMID 24338153, 2014). "For instance, lentivirus-mediated AQP5-shRNA transduction or hyperosmotic stress induced by sorbitol in MCF7 breast cancer cell line lead to attenuation of cell proliferation and migration." (PMID 25344048, 2014). "The authors concluded that AQP5 over-expression plays a role in cell growth and metastasis in human breast cancer." (PMID 24338153, 2014). "Jung and co-workers detected AQP5 mRNA and protein in the human breast cancer cell lines MCF7 and MDA-MB-231 by RT-PCR and immunoblotting." (PMID 24338153, 2014). "In this study, we demonstrated that AQP5 is likely to play a role in proliferation and migration of human breast cancer cells." (PMID 22145049, 2011). "In the present study, AQP5 mRNA and protein are expressed in human breast cancer cell lines, MCF7 and MDA-MB-231, both of which are originated from breast ductal epithelial cells." (PMID 22145049, 2011). "RT-PCR and immunoblotting analysis revealed the expression of AQP5 mRNA and protein in human breast cancer cells and immunohistochemistry demonstrated AQP5 labeling in the ductal epithelial cells of human breast tissues." (PMID 22145049, 2011). "Expression of AQP5 mRNA and protein was seen in human breast cancer cell line (both MCF7 and MDA-MB-231) by RT-PCR and immunoblotting analysis." (PMID 22145049, 2011). "The change of AQP5 expression in breast cancer cells was examined in response to extracellular hyperosmotic stress induced by sorbitol-containing medium." (PMID 22145049, 2011). "Expression of AQP5 mRNA and protein was investigated in human breast cancer cell lines (both MCF7 and MDA-MB-231 cells) by reverse transcriptase-PCR (RT-PCR) and immunoblotting analysis." (PMID 22145049, 2011). "Thus, the results demonstrated an intense AQP5 labeling in the invasive cancer cells combined with the gradual decrease of AQP5 labeling in the ductal cells, along with the loss of AQP5 polarity in the apical plasma membrane domain during the progression of breast carcinoma." (PMID 22145049, 2011). "Immunoblotting analysis also revealed that both human breast cancer cell lines express AQP5 protein." (PMID 22145049, 2011). "In the present study, we also demonstrated significantly decreased cell proliferation and migration of human breast cancer cells with shRNA- or hyperosmotic stress-mediated AQP5 knockdown." (PMID 22145049, 2011). "This expression profile in CML is comparable to that in solid tumors; AQP5 is expressed in 35% (144/408) of non-small-cell lung cancer, and similar observations were also found in breast cancer (manuscript in preparation)." (PMID 18612408, 2008). "Since AQP5 has been suggested to play a role in breast cancer cell proliferation, we investigated whether AQP5 overexpression affects PI3K/AKT signaling." (PMID 40244097, 2025).
breast carcinoma (continued). "Similarly strong correlations between aquaporin expression and cellular proliferation have also been observed in other tumors (e.g., AQP1 in lung cancer 19 and AQP5 in breast cancer 20)." (PMID 40225573, 2025). "Similarly, miR-1226-3p, miR-19a-3p and miR-19b-3p suppress AQP5 expression in breast cancer, contributing to reduced cell migration." (PMID 39941100, 2025). "Moreover, AQP5 inhibition not only reversed Adriamycin resistance of breast cancer cells but reduced the IC50 of Adriamycin in MCF-7 cells." (PMID 39123442, 2024). "Likewise, the identification of three AQP5 mediating miRNAs (miR-19a-3p, miR-1226–3p, and miR-19b-3p) which reduce breast cancer cell motility by lowering AQP5 translation supports the concept of additional research to prove it as potential therapeutic target." (PMID 38336645, 2024). "Demographics of the breast cancer patients with strong AQP5 expression and tumor characteristics." (PMID 36706090, 2023). "In order to efficiently deliver miRNAs targeting AQP5 to breast cancer cells, the researchers designed exosomes that express both miRNAs and a peptide targeting the interleukin-4 receptor, which is known to be highly expressed in breast cancer cells." (PMID 38136293, 2023). "Moreover, by multivariate analysis adjusting histologic grade and tumor stage, AQP5 overexpression (212 cases) in breast cancer is correlated with a poorer disease specific survival rate (p = 0.035; RR = 1.567; 95% CI 1.032–2.375)." (PMID 36706090, 2023). "We envision that an anti AQP5 therapeutic antibody or small molecular inhibitors targeted to AQP5 expression among BC patients with strong AQP5 expression or genomic implications may open door to new levels of anti-breast cancer therapeutics." (PMID 36706090, 2023). "Therefore, we will further discuss two aquaporins AQP3 and AQP5, representing glyceroaquaporin and orthodox aquaporin in details for their role in breast cancer." (PMID 33947079, 2021). "Indeed, the discovery of three AQP5-regulating miRNAs (miR-1226–3p, miR-19a-3p, and miR-19b-3p) that, by decreasing the translation of AQP5, reduce breast cancer cell migration, supports its further investigation as a possible therapeutic target." (PMID 33947079, 2021). "For example, AQP5 is overexpressed in ovarian cancer, cervical cancer, and breast cancer." (PMID 32462020, 2020). "Silencing AQP5 in an ER-positive breast cancer cell line (MCF7) significantly reduced cell proliferation and migration, strongly suggesting that AQP5 may play a role in the cell growth and metastasis of human breast cancer." (PMID 31379986, 2019). "A significant AQP5 upregulation found in tumors from early breast cancer patients indicates it may be used as a prognostic marker." (PMID 31379986, 2019). "While AQP3 overexpression in early breast cancer patients was shown to be associated with a worse prognosis in patients with the HER2-overexpressing phenotype, AQP1 and AQP5 were reported as independent prognostic markers of survival for breast cancer patients." (PMID 31379986, 2019). "There is an increased expression of AQP1, AQP3, and AQP5 in breast cancer." (PMID 30555637, 2018). "AQP5 is understood to regulate proliferation and migration of breast cancer cells and may be used as a prognostic marker." (PMID 30555637, 2018). "Similarly, knockdown of AQP5 in MCF7 breast cancer cells resulted in significantly reduced proliferation and migration." (PMID 26912239, 2016). "The expression of AQP1, AQP3, and AQP5 is up-regulated in breast cancer." (PMID 25886458, 2015). "Interestingly, mammary tumor libraries showed increased AQP5 mRNA levels, whereas mRNA libraries of normal mammary glands of lactating mice showed low levels." (PMID 25767807, 2015). "For example, AQP5 overexpression is related to cell growth and metastasis in human breast cancer." (PMID 24918928, 2014). "Moreover, immunohistochemistry revealed the localization of AQP5 at the ductal epithelial cells of human breast cancer tissues." (PMID 22145049, 2011).